CCL22 (C-C motif chemokine ligand 22)
Diseases named in the same sentence as CCL22 in open-access papers (continued):
Sharing a sentence is not in itself a finding about the gene and the disease.
cancer (continued). "For example, CCR1, IL1RAP, CCL22 and CSF1 are all involved in metastatic dissemination, and their aberrant expression correlates with leukocyte infiltration and aggressive phenotype in various cancer types." (PMID 26536459, 2015). "Furthermore, DTX with RS significantly decreased the production of CCL22 and CCL18, which was previously reported to correlate with the severity and prognosis in cancer patients." (PMID 24489574, 2013). "However, we did not observe a ZEB1-dependent effect on proliferation of CD8 + T cells in vitro when co-cultured with BMDMs, but a ZEB1-dependent modulation of CD8 + T cell migration by CCL2 and CCL22 as well as CCR2 and CCR4 expression in CD8 + T cell subsets in murine and human cancers." (PMID 40595293, 2025). "Recent studies have shown that TAMs play an important role in immune-mediated cancer control through the secretion of multiple cytokines, including IL-6, IL-10, transforming growth factor β (TGF-β), tumor necrosis factor α (TNF-α), C-C chemokine motif ligand 18 (CCL18) and CCL22." (PMID 40369674, 2025). "Additionally, an analysis of COAD and adjacent non-cancerous tissue samples from the TCGA database confirmed significant increases in CXCL1, CXCL8, CXCL9, and CXCL11 in cancer tissues, while CCL22 showed no significant change." (PMID 38791448, 2024). "For both cancer specimens and macrophages, we demonstrated significantly decreased Treg attraction upon incubation with curcumin alone, as well as curcumin in combination with PIC, which is in line with decreased CCL22 chemokine expression after combinatorial treatment." (PMID 33809574, 2021). "Interestingly, both these effective combinations showed at least partial selectivity in inducing CXCL10 (rather than CCL22) in cancer tissues." (PMID 25806105, 2015). "Subsequently, cancer cells together with osteoblasts may induce secretion of fibroblast growth factor (FGF), transforming growth factor-beta (TGF-beta), or chemokines such as: C-C motif chemokine 22 (CCL22) or receptor activator for nuclear factor κ B ligand (RANKL)." (PMID 31731466, 2019). "In conclusion, we verified the differential expression of HOTAIR and CCL22 in cancer tissues and adjacent normal tissues in NSCLC patients, and there was a strong negative correlation between HOTAIR and CCL22 mRNA expression." (PMID 35176085, 2022). "For example, while neither (mf or cancer cell lines) induces the production of CCL4, TNF-α, IL-10, or VEGF, they both significantly enhance the production of IP-10 and CCL22 in human monocytes." (PMID 29668679, 2018). "To evaluate whether the prognostic value of the CCL22 and TNFSF10 score was independent of known clinical variables, we assessed the biomarker in different clinical cohorts, stratified by gender and cancer type." (PMID 41295982, 2026). "CCL18, CCL22, CCL23, and CXCL12 consistently showed a negative correlation across most cancer types, while other anti-inflammatory chemokine genes displayed a more complex, context-dependent relationship, with both positive and negative correlations depending on the specific malignancy." (PMID 40806276, 2025). "In addition, the secretion of CCL12, CCL22, and CCL24 was higher in the group without cancer cell spheroids (M1), indicating an inhibitory effect of spheroids on these chemokines." (PMID 37445941, 2023). "Several genes were also, however, inconsistent with the mouse model data including CCL5, CCL20, CCL22, CCL28, CXCL10, and PDL2, suggesting that these features may not be as robustly tissue-specific across different primary cancers." (PMID 33985562, 2021).
infection (58 papers, 2010 to 2025). The state of being infected such as from the introduction of a foreign agent such as serum, vaccine, antigenic substance or organism. "Several proteins including CCL22 showed to be associated with persistent radiological abnormalities at ten months post-infection." (PMID 39324144, 2024). "Conversely, expression of the pro-inflammatory IL18 in the jejunum was significantly decreased by infection (fold change − 1.2), and so were type-2 associated gene CCL22 (fold change − 2.1) and adipocyte regulator PPARG (fold change − 1.3)." (PMID 38081984, 2023). "Together, these data suggest that baseline myeloid and lymphocyte chemoattractant CCL13 and CCL22 levels in the nose, primarily produced by DCs, may be associated with prevention of infection." (PMID 41354730, 2025). "Furthermore, infection with filarial parasites resulted in upregulation of CCL22, a type-2 associated chemokine, both at the mRNA levels and by its observed effect on the frequency of recruited monocytes." (PMID 34106920, 2021). "In contrast, 4T1-upregulated Ccl7, Ccl12 and Ccl22 (most strongly upregulated by SFV/TNFα) were even more upregulated after infection." (PMID 40547518, 2025). "One gene, CCL22, which is upregulated in phagocytosed group, was notably expressed in exposed DCs and B cells 24h post-infection." (PMID 40630957, 2025). "In contrast, CCL22 is only detected in large quantities following infection of PHT cells with T. gondii and in trophoblast organoids after infection." (PMID 38771057, 2024). "The lower levels of CCL22/MDC in comparison with healthy donors raises the question of the potential depletion of this chemokine mid-infection, or the involvement of CCL22/MDC in the viral cycle of SARS-CoV2." (PMID 36012323, 2022). "Recently, we found that primary human trophoblast cells (derived from term placentas) and second trimester placental explants produced the chemokine CCL22 in response to infection with T. gondii." (PMID 34781732, 2021). "Prior work showed that T. gondii infection dramatically and specifically increases the secretion of the immunomodulatory chemokine CCL22 in human placental cells during infection." (PMID 34781732, 2021). "Nevertheless, infection with filaria significantly upreguled the frequency of CCL22+monocytes, IL-10+mDCs and regulatory T cells." (PMID 34106920, 2021). "While T. gondii induces CCL22 during infection of a variety of cell types from both mice and humans, including at the transcriptional level in mouse brain, placental cell CCL22 induction is driven by a highly specific parasite effector, GRA28." (PMID 34781732, 2021). "Based on previous results, we resorted to a murine model of CF challenged with A. fumigatus and first evaluated the expression of CCR4 and its ligands CCL17 and CCL22 during infection." (PMID 33669094, 2021). "Overall, these data indicate that the process driving T. gondii GRA28-induced Ccl22 is similar, if not the same, in both mice and humans and that this parasite effector can mediate robust changes in Ccl22 production at the site of infection and systemically." (PMID 34781732, 2021). "Of the three genes with significantly higher transcript levels (Ccl22, Il12rb2, Ccr7) in wild-type 1 infections compared to RHΔGRA28 infections, Ccl22 was the most highly induced." (PMID 34781732, 2021). "It is feasible that the altered macrophage compartment in these knockout animals further promotes a Th2 response by releasing CCL17 and CCL22 chemokines known to recruit Th2 cells to the site of infection." (PMID 31365119, 2019). "Second-trimester human placental villi resist T. gondii infection and induce CCL22 in response to infection." (PMID 29317509, 2018). "Because CCR4 deficiency increases susceptibility in the chronic phase of infection, we next assessed the gene expression of CCR4 and its ligands CCL17 and CCL22." (PMID 30584243, 2018).
infection (continued). "(F) CCL17 and CCL22 levels were measured by ELISA from supernatants collected 24 hr after BMDM infection with the indicated strains at an MOI of 1:5." (PMID 30320549, 2018). "Accordingly, we found increased RNA abundance of Arg1, Socs1, Sra1, Saa1, Ciita, Marco, Mgl2, Cd209d, Cd209e, Cd209f, Ccl1, Ccl11, Ccl17, Ccl19, Ccl20, Ccl22, and Ccl24 genes in Stat2−/− mice when compared to WT mice during super-infection." (PMID 30337919, 2018). "Following infection, expression levels of the immunomodulatory cytokines C-C motif chemokine 22 (CCL22), CCL1, IL-23α, IL-3, IL-4, matrix metalloproteinase 9 (MMP9), IL-21, C-X-C motif chemokine 2 (CXCL2), and CCL2 were increased." (PMID 28507072, 2017). "Expression of the type 2 chemokine ligands, CCL17 and CCL22 increased as early as 7 days post-infection and remained upregulated up to 21 days of infection, but somewhat surprisingly their receptor, CCR4, was not." (PMID 28103263, 2017). "While this activity and the regulation of Th17 cells may generally be considered beneficial during infection, the expression of ccr7 and ccl22 may suggest otherwise." (PMID 40682363, 2025). "Notably, cytokine family members Ccl2, Ccl3, Ccl4, Ccl5, Ccl7, Ccl9, and Ccl22 were also significantly activated following infection." (PMID 40539063, 2025). "While the role of CCL22 during infection with T. gondii is poorly understood, this chemokine is a key molecular signal for the recruitment of regulatory T cells, which are well known for their role in suppressing immune responses to tumors, leading to poor clinical outcomes." (PMID 34781732, 2021). "In the context of macrophages infection, GRA18 induces the expression of a specific set of genes commonly associated with an anti-inflammatory response that includes those encoding chemokines CCL17 and CCL22." (PMID 30320549, 2018). "In addition to resisting T. gondii infection, our data show that PHT cells robustly induce the chemokine CCL22 in response to infection by a MYR1-dependent effector secretion mechanism." (PMID 29317509, 2018). "Next, we found increased mRNA expression and activity levels of Arg1, mRNA expression of Fizz, Chi3l3, Cd209d, Cd209e, Mrc2 (Cd206), Marco, Il13, Saa1 (Serum amyloid A1 protein), Ccl17, Ccl19, Ccl20, Ccl22, and Ccl24 in Stat2−/− mice compared to WT mice during super-infection." (PMID 30337919, 2018). "However, M2-related chemokines CCL2, CCL17, and CCL22 progressively increased during the period of 13 weeks infection." (PMID 24666892, 2014). "Toxoplasma-induced accumulation of β-catenin in the host cell nucleus, and the dysregulation of CCL22 is reportedly induced by a dense granule (GRA) protein (GRA18) that is secreted beyond the parasites' parasitophorous vacuole membrane (PVM) into the host cell during infection." (PMID 33014886, 2020). "Given that CCL22 levels are elevated in maternal serum during healthy, infection-free pregnancies, CCL22 and its recruitment of regulatory T cells may also play a role in immune tolerance throughout gestation, which is modulated in response to infection." (PMID 29317509, 2018). "We also observed a very tight correlation between parasite multiplicity of infection (MOI) and CCL22 levels, suggesting that the signal was driven primarily by the parasite rather than the host cell." (PMID 34781732, 2021). "Consequently, we propose the following hypothesis in which the infection using Δgra18 strains, which may provide a weaker Th2 chemokine profile (Ccl17, Ccl22, and Ccl24) led to early control and lower chance for long-term persistence in mice than GRA18 wild type parasites." (PMID 30320549, 2018). "We found that 172 transcripts were differentially expressed in response to T. gondii infection of villous explants, with 22 of these transcripts also being differentially expressed in response to infection of PHT cells, which included EGR3, EGR4, and CCL22." (PMID 29317509, 2018).
infection (continued). "Our results showed that the majority of chemokines and receptors were up-regulated more strongly in the CVS-11 infection than the HEP-Flury at a later stage, besides CCL22, CXCR3, CXCR6, and CCR7." (PMID 27242764, 2016). "Among other genes found to display high, and significant expressional levels during infection were IL-1α, IL-32, growth differentiation factor 15 (GDF15) and, chemokine (C-C motif) ligand 22 (CCL22)." (PMID 23646188, 2013). "Chemokine measurement 6 hours post bacterial infection showed similar trends in some cytokines, but also highlighted the importance of cytokine kinetics within infection, as multiple chemokines were altered only at early time points, including CCL17, CCL22, IL-6, and CXCL5." (PMID 39178311, 2024). "In contrast, YKL-40 and CCL22 consistently trended to decrease post-infection, whereas other cytokines showed no consistent pattern." (PMID 37012228, 2023). "In addition, the functional state CS3 is the most different with the expression of Cd86, Cd4, and especially Ccl22, suggesting this state to be actively recruiting other cells, such as invariant NKT or regulatory T cells, in response to the infection." (PMID 34404761, 2021). "Consistent with previous findings, LCMV-infected WT mice showed a significant increase of CCL2 on day 3 postinfection and IL-5 on day 7 postinfection, only, while TNF, IL-1β, IL-6, IFN-γ, CCL1 and CCL22 levels did not change following infection." (PMID 32310998, 2020). "Modulation of some chemokine transcripts, such as ccl12 or ccl22 was observed (Figure 4B2), which did not translate into a corresponding increase in secreted proteins after only 24 h of infection." (PMID 32582184, 2020). "Similarly, CCL19, CCL22, and CXCL13 were significantly upregulated by a primary infection in the R line of the HSF flock when compared to its S line counterparts." (PMID 30678719, 2019). "On the other hand, S. mansoni treated hMDMs expressed higher levels of CCR7 (M1 macrophages;), produced less IL-10 during infection, showed no elevation in CCL22 and were also more fit to control Mtb." (PMID 28192437, 2017). "On the other hand, the levels of CCL17, CCL21 and CCL22 were not affected by FusOn-H2 infection, and CCL5 was actually reduced by the virus treatment." (PMID 25460506, 2015). "In addition to early induction of CXC chemokines, we also show that induction of genes encoding C-C chemokines namely CCL-2 (MCP-1), CCL8 (MCP-2), CCL12 (MCP-5) and CCL22 (MDC) occurs on D12 and progressively increases between D15 and D21 post infection." (PMID 21249199, 2011). "Together, interactions among multiple molecules consisting of this network, such as CD19, CD 22, and CD79A/B, and chemokines including CCL19, CCL22, and CXCL13 may contribute to enhanced immune responses in the resistant line in the HSF flock to the innate infection." (PMID 30678719, 2019). "Since we also found that not all cell types produce CCL22 in response to infection (e.g., human foreskin fibroblasts [HFFs]), we were interested in identifying a human cell line that could be used as a more tractable model than placental cells to assay T. gondii-driven CCL22 induction." (PMID 34781732, 2021).
bacterial infections (5 papers, 2019 to 2025). "Most of these chemokines and cytokines, such as CCL5, CCL22, IL-1β, and TNF-α, are critical to “pre-condition” the lungs to become invulnerable to bacterial infections or promote bacterial clearance during lung infections." (PMID 35677203, 2022).
cardiovascular disease (3 papers, 2020 to 2025). "Our follow-up study also needs to further confirm whether CCL22 has the same or opposite regulatory mechanism as CCL17 in cardiovascular diseases." (PMID 41266856, 2025). "In summary, the hub genes related with M2 macrophages that we searched include CCL22, C1orf105, GAP43, and PTPN21, all of which imply a relationship with cardiovascular disease, which is consistent with our findings." (PMID 36222281, 2022).
inflammation (2 papers, 2015 to 2022). Aberrant reaction of the microcirculation characterized by movement of fluid and leukocytes from the blood into extravascular tissues. "We describe here the identification of high affinity neutraligands of CCL17 and CCL22, two chemokines involved in the Th2-type of lung inflammation." (PMID 26442456, 2015).
neurodegenerative disease (2 papers, 2023). A disorder of the central nervous system characterized by gradual and progressive loss of neural tissue and neurologic function. "CCL22 has been found to be implicated in MS; however, to the best of our knowledge, there have been no studies indicating CCL22 elevation in age-related neurodegenerative diseases." (PMID 37408205, 2023).
benign tumors (1 paper, 2015). "Interestingly, our data suggest that malignant and benign tumors induce significantly different levels of CCL22 secretion." (PMID 25647263, 2015).
colorectal (1 paper, 2022). "This study provides several supporting lines of evidence that highlight the critical role of CCL22 in F. nucleatum-related colorectal tumorigenesis and its close relationship with the TME and ICIs, which deserved further cell and animal experiments." (PMID 35295948, 2022). "In summary, our study provided evidence that CCL22 might play a crucial role in F. nucleatum-related colorectal tumorigenesis and correlate with TME and ICIs, which deserves further study." (PMID 35295948, 2022).
immune disorders (1 paper, 2018). "CCL22 and its receptor contribute to the onset or development of immune disorders by inducing changes in the expression and contribution or the functions." (PMID 30467506, 2018).
renal diseases (1 paper, 2020). "Note that various types of macrophages infiltrate into the kidney after renal diseases, that CCL22/17 are expressed in CD206+ M2‐like type macrophages, and that the transfer of CD206+ M2 macrophages ameliorates pathology in the cGN model." (PMID 33163184, 2020).
CCL22 also shares sentences with these, for which no sentence is quoted: Allergy (9 papers); colorectal adenocarcinoma (4); idiopathic pulmonary fibrosis (4); adenocarcinoma (3); systemic lupus erythematosus (3); allergic rhinitis (2); cervical squamous cell carcinoma (2); Crohn disease (2); depression (2); esophageal cancer (2); nasopharyngeal carcinoma (2); pseudoexfoliation glaucoma (2); pulmonary edema (2); squamous carcinoma (2); acute myeloid leukemia (1); acute myocardial infarction (1); acute pancreatitis (1); adult onset asthma (1); AIDS (1); allergic contact dermatitis (1); B-cell non-Hodgkin lymphoma (1); bacteremia (1); Carcinoid (1); cervical tumor (1); cholelithiasis (1); co-infection (1); cognitive decline (1); colorectal tumor (1); conjunctivitis (1); Cutaneous T-Cell Lymphoma (1).
A further 52 diseases each share a sentence with CCL22 in 1 paper.